SOD1 (superoxide dismutase 1)
Diseases named in the same sentence as SOD1 in open-access papers (continued):
Sharing a sentence is not in itself a finding about the gene and the disease.
amyotrophic lateral sclerosis (continued). "Hallmarks of CNS inflammation, including microglial and astrocyte activation, are prominent features in post-mortem tissue from amyotrophic lateral sclerosis (ALS) patients and in mice overexpressing mutant superoxide dismutase-1 (SOD1G93A)." (PMID 24923195, 2014). "The second mouse line, Tg(SOD1G93A)dl1/GurJ (referred to as SOD1 mice), models the human condition of amyotrophic lateral sclerosis (ALS)." (PMID 24423792, 2014). "Familial amyotrophic lateral sclerosis (ALS) occurs due to the accumulation of mutant superoxide dismutase 1 (mSOD1) in neuronal cells." (PMID 27419207, 2014). "In amyotrophic lateral sclerosis (ALS), aggregates of misfolded superoxide dismutase 1 (SOD1) propagate in a spatiotemporal manner linking upper and lower motor neurons." (PMID 22610588, 2013). "We treated transgenic mice that over-express human mutant superoxide dismutase 1, a model of amyotrophic lateral sclerosis, with busulfan to determine whether this commonly used chemotherapeutic leads to stable chimerism and promotes the entry of bone marrow-derived cells into spinal cord." (PMID 23593276, 2013). "Intriguingly, while astrocyte-conditioned medium derived from mice transgenic for wild-type human SOD1 mimics the effect of wild-type astrocytes, conditioned medium derived from astrocytes carrying an amyotrophic lateral sclerosis-related SOD1-G93A mutation shows no such beneficial effect." (PMID 24134124, 2013). "For example, in amyotrophic lateral sclerosis (ALS), the misfolded proteins like SOD1 released initially from motor neurons activate microglia, and the ensuing neuronal injury depends upon a well-orchestrated dialogue between motor neurons and microglia." (PMID 23844272, 2013). "Anterograde and retrograde trafficking is altered in Amyotrophic lateral sclerosis (ALS) mouse models in which SOD1, guanin-nucleotide exchange factor (GEF) and TAR DNA-binding protein 43 (TDP-43) are mutated." (PMID 22792111, 2012). "Mutations in the SOD1, TARDBP, and FUS genes have been commonly identified in Amyotrophic Lateral Sclerosis (ALS)." (PMID 21829392, 2011). "Mutations in the SOD1 and TARDBP genes have been commonly identified in Amyotrophic Lateral Sclerosis (ALS)." (PMID 21829392, 2011). "Accumulation of misfolded neurotoxic Cu, Zn-superoxide dismutase-1 (SOD1) protein found in both familial and sporadic amyotrophic lateral sclerosis (ALS) is recognized as an important contributing factor of neuronal cell death." (PMID 21548977, 2011). "We recently reported the presence of a novel 32 kDa protein immunoreactive to a copper, zinc superoxide dismutase (SOD1) antibody within the spinal cord of patients with amyotrophic lateral sclerosis (ALS)." (PMID 21152319, 2010). "The G-CSF receptor and G-CSF itself are expressed in α motoneurons, G-CSF protects motoneurons, and improves outcome in the SOD1(G93A) transgenic mouse model for amyotrophic lateral sclerosis (ALS)." (PMID 20178614, 2010). "In the SOD1 transgenic mouse model of amyotrophic lateral sclerosis (ALS) the exclusion of mutant SOD1 expression in microglial cells is associated with decreased inflammation and an extension of life span." (PMID 20701773, 2010). "These proteins are more often thought of in the context of neurodegenerative diseases (PrP, mad cow disease; Aβ, Alzheimer disease (AD); and SOD1, Amyotrophic lateral sclerosis (ALS)/Lou Gehrig's disease)." (PMID 20819221, 2010). "Interestingly, it was recently demonstrated that inactivation of the Nox2 gene in the mutant Sod1 mouse model for amyotrophic lateral sclerosis significantly increased survival when mice were of mixed genetic background, but had very modest effect on the inbred C57Bl/6 strain." (PMID 19340302, 2009). "Mutations in SOD1 in a subset of familial amyotrophic lateral sclerosis (ALS) cases confer dominant but clinically variable toxicity, thought to be mediated by misfolding and aggregation of mutant SOD1 protein." (PMID 19266020, 2009).
amyotrophic lateral sclerosis (continued). "In amyotrophic lateral sclerosis (ALS), the potential of IADB to regulate autophagy has been explored in preclinical studies, demonstrating reductions in mutant SOD1 aggregates and attenuation of astrocyte activation." (PMID 40940752, 2025). "For instance, in Amyotrophic Lateral Sclerosis (ALS), the effectiveness of ubiquitin–proteasome system (UPS)-mediated degradation of mutant superoxide dismutase 1 (SOD1) is a subject of ongoing debate." (PMID 41226604, 2025). "The prion-like behavior of protein aggregates is further supported by evidence from studies on amyotrophic lateral sclerosis (ALS), where misfolded superoxide dismutase-1 (SOD1) aggregates have been shown to propagate in a prion-like manner." (PMID 41226604, 2025). "As evidence, the FDA approval of Tofersen, an antisense oligonucleotide for the treatment of SOD1 amyotrophic lateral sclerosis (ALS), on 25 April 2023 is based on changes in blood NfL levels, outlining a major change in the landscape of what biomarkers mean for regulatory approvals." (PMID 40076577, 2025). "The RfxCas13d system has also been used in silencing targeted mRNA to improve outcomes in the nervous system (SOD1 and HTT in a model of amyotrophic lateral sclerosis and Huntington’s disease, respectively)." (PMID 38972974, 2024). "We further evaluated the OFIC approach with even lower input samples, then used this method to determine how the proteome is impacted by loss of superoxide dismutase sod-1, the ortholog of human SOD-1, a gene associated with amyotrophic lateral sclerosis (ALS)." (PMID 39345438, 2024). "Here, we present the PTMs and PTVs of four major amyotrophic lateral sclerosis (ALS) proteins, SOD1, TDP-43, FUS, and TBK1." (PMID 39201350, 2024). "In vitro studies have demonstrated that ADSC-derived EVs can alter the cellular phenotype of amyotrophic lateral sclerosis (ALS), including reducing aggregation of superoxide dismutase 1 and improving mitochondrial function, indicating their potential therapeutic use in ALS." (PMID 39000150, 2024). "There are three known forms of SOD in humans, in which mutations in the gene encoding copper, zinc superoxide dismutase 1 (Cu, Zn-SOD1) are associated with amyotrophic lateral sclerosis (ALS)." (PMID 36817952, 2023). "In amyotrophic lateral sclerosis (ALS), several polypeptides are inclined to misfold and aggregate, such as Tar DNA binding protein-43 (TDP-43), superoxide dismutase 1 (SOD1) and ubiquilin-2." (PMID 37107340, 2023). "Additionally, SOD1, the oxidative stress-related protein, promotes amyotrophic lateral sclerosis (ALS)." (PMID 36551187, 2022). "In muscular models characterized by atrophy and fibrosis, such as dystrophic mdx muscles or muscles from SOD1-G93A mice, a transgenic model of ALS (amyotrophic lateral sclerosis) and an increased expression of Pde5a1 were observed." (PMID 36614143, 2022). "In amyotrophic lateral sclerosis (ALS), related studies have found that misfolded SOD1 protein can be transferred from cell to cell through exosomes dependence and exosomes independence, make progating diaeases." (PMID 35335993, 2022). "In one trial 2 patients with familial amyotrophic lateral sclerosis (ALS) and mutations in the gene encoding superoxide dismutase 1 (SOD1) were treated with a single intrathecal infusion of an AAV vector encoding a microRNA targeting SOD1." (PMID 36032092, 2022). "These include protein aggregates formed by hyperphosphorylated tau in Alzheimer’s disease, mutant superoxide dismutase 1 (SOD1), and TAR DNA–binding protein 43 (TDP-43) in amyotrophic lateral sclerosis, and mutant huntingtin (Htt) in HD." (PMID 35780830, 2022). "However, there are no significant changes in CSF SOD1 levels in amyotrophic lateral sclerosis, including sporadic or SOD1 mutation carriers, suggesting that SOD1 may not be an effective biomarker for amyotrophic lateral sclerosis." (PMID 35202463, 2022).
amyotrophic lateral sclerosis (continued). "Mutant superoxide dismutase 1 (SOD1) can be constitutively released from motor neurons and transmitted to naïve motor neurons to promote the progression of amyotrophic lateral sclerosis (ALS)." (PMID 35478453, 2022). "Comparison of our B cells with those isolated from the meninges of SCI and SOD1 mice, a model of amyotrophic lateral sclerosis (ALS), showed the B cells we isolated from the spinal cord were most similar to those found in the meninges under inflammatory conditions." (PMID 36333772, 2022). "Since the discovery of Cu/Zn superoxide dismutase (SOD1) gene mutation, in 1993, as the first genetic abnormality in amyotrophic lateral sclerosis (ALS), over 50 genes have been identified as either cause or modifier in ALS and ALS/frontotemporal dementia (FTD) spectrum disease." (PMID 35805149, 2022). "For example, in the zebrafish model of amyotrophic lateral sclerosis (ALS), overexpression of mutant SOD1 leads to aberrant branching and shortening of the primary motor axons, whereas knockdown of C9orf72, associated with ALS, causes aberrant branching of CaP motor axons." (PMID 33973627, 2021). "BDNF is reported to slow the progression of motor neuron atrophy in an animal model of amyotrophic lateral sclerosis (ALS), and the TrkB agonist 7,8-dihydroxyflavone (7,8-DHF) improved motor neuron deficits in the superoxide dismutase 1 (SOD1G93A) ALS mouse models." (PMID 34833132, 2021). "Superoxide dismutase 1 (SOD1) is a metalloenzyme with high structural stability, but a lack of Cu and Zn ions decreases its stability and enhances the likelihood of misfolding, which is a pathological hallmark of amyotrophic lateral sclerosis (ALS)." (PMID 33923808, 2021). "The relevance of this EAAT2-derived signaling mechanism was demonstrated in vivo, in a mutant SOD1 mouse model of amyotrophic lateral sclerosis (ALS), where knock-in of a modified Slc1a2 isoform with a defective caspase-3 cleavage site prolonged the life span of mice afflicted by the disease." (PMID 35173582, 2021). "Furthermore, we investigated VCE-006.1 in two genetic models of amyotrophic lateral sclerosis (ALS), mutant SOD1, or TDP-43 transgenic mice." (PMID 34946726, 2021). "In the case of amyotrophic lateral sclerosis (ALS), superoxide dismutase 1 has been investigated intensely as it was the first gene shown to be mutated in familial forms of the disease." (PMID 34803658, 2021). "Moreover, the synthetic PPARγ agonist pioglitazone was shown to extend the survival of SOD1-G93A, a mouse model of Amyotrophic lateral sclerosis (ALS), by delaying the onset of the disease and preventing the death of motor neuron cells." (PMID 33799988, 2021). "Moreover, through EB1/EB3 interactions, NAP enhances Tau-microtubule binding, protecting against tauopathy, which has also been found in the SOD1-G93A mouse model of the neuromuscular disorder, amyotrophic lateral sclerosis (ALS)." (PMID 32937737, 2020). "Superoxide dismutase 1 (SOD1) is a Cu-Zn metalloprotein that catalyzes the dismutation of the superoxide anion, and its disfunction is correlated with the progressive neurodegenerative disease, amyotrophic lateral sclerosis (ALS)." (PMID 33187056, 2020). "SOD1 was shown by KEGG to be involved in diverse pathways, i.e., longevity regulating pathway, amyotrophic lateral sclerosis (ALS), prion diseases, peroxisome, and Huntington’s disease." (PMID 32183175, 2020). "Moreover, astroglia can express NLRP3 inflammasome and IL-1β under certain conditions, such as in SOD1 mouse model of amyotrophic lateral sclerosis (ALS) and human sporadic ALS patients, and amyloid β1–42-stimulated murine astrocytes." (PMID 32070376, 2020). "As an example, mutant superoxide dismutase-1 (mSOD1), one of the gene products responsible for amyotrophic lateral sclerosis (ALS), aggregates due to its conformational changes, accumulates in mitochondria, and inhibits mitochondrial protein transport, thereby impairing mitochondrial function." (PMID 32471110, 2020).
amyotrophic lateral sclerosis (continued). "In a murine model of amyotrophic lateral sclerosis (ALS), a short treatment with clemastine (from postnatal day 40 to day 120) could delay the disease onset and extend the survival of SOD1-G93A mice by ~10%." (PMID 32477120, 2020). "SOD1 mutations are the most common cause of amyotrophic lateral sclerosis (ALS) in non-Caucasian patients." (PMID 30637102, 2019). "Likewise, aggregation of Superoxide Dismutase (SOD1) is believed to be responsible for Amyotrophic Lateral Sclerosis (ALS)." (PMID 31536559, 2019). "Abnormal cytoplasmic accumulation of fused in sarcoma (FUS) protein is the pathological hallmark of some cases of amyotrophic lateral sclerosis (ALS) with transactive response DNA‐binding protein of 43KDa (TDP‐43)‐negative pathology that lack SOD1 mutations." (PMID 30375034, 2019). "Recent studies experimentally investigated the role of the SOD1 in ALS (Amyotrophic lateral sclerosis), finding an alteration of the glutamate release in the mice spinal cord, while other ones found abnormal expression of the SOD1 in patients affected by neuronal disorders." (PMID 31454403, 2019). "In a mouse model of motor neuron disease/amyotrophic lateral sclerosis (ALS) due to overexpression of mutant superoxide dismutase (SOD)-1, significantly increased levels of Grn mRNA and PGRN protein were detected in spinal cord samples after disease symptoms had started." (PMID 30862089, 2019). "Importantly, these loop regions have been directly implicated in the misfolding and subsequent cytotoxic aggregation of SOD1, which lead to the fatal neurodegenerative implications and a diseased state termed amyotrophic lateral sclerosis (ALS)." (PMID 31817166, 2019). "Interestingly, in most neurodegenerative diseases – such as ALS-amyotrophic lateral sclerosis, Parkinson's and Alzheimer's – SOD1 dysfunction, mitochondrial fragmentation and bioenergetics deficiencies occur; similar events may occur in diabetic retinal neurodegeneration." (PMID 31023645, 2019). "Non-natively folded variants of superoxide dismutase 1 (SOD1) are thought to contribute to the pathogenesis of familial amyotrophic lateral sclerosis (ALS), however the relative toxicities of these variants are controversial." (PMID 31040321, 2019). "Degeneration of cortical and spinal motor neurons is the typical feature of amyotrophic lateral sclerosis (ALS), a progressive neurodegenerative disease for which a pathogenetic role for the Cu/Zn superoxide dismutase (SOD1) has been demonstrated." (PMID 30154836, 2018). "In amyotrophic lateral sclerosis (ALS) and animal models of ALS, including SOD1-G93A mice, disassembly of the neuromuscular synapse precedes motor neuron loss and is sufficient to cause a decline in motor function that culminates in lethal respiratory paralysis." (PMID 29460776, 2018). "For a long time amyotrophic lateral sclerosis (ALS) research depended on only a few mouse models that exhibit a very strong and early phenotype, e.g. SOD1 mice, resulting in a short treatment time window." (PMID 29787578, 2018). "In a murine model of the motor neuron disorder amyotrophic lateral sclerosis (ALS), microglia from SOD1-G93A mice, which spontaneously develop an ALS phenotype, appear to be responsive to histamine through H1R and H4R, leading to a reduction in the inflammatory state." (PMID 30224900, 2018). "By contrast, overexpression of Parkinson’s disease-linked alpha-Synuclein or Amyotrophic Lateral Sclerosis (ALS)-linked human SOD1 in larval eye disc failed to elevate Acn S437 phosphorylation compared to wild type." (PMID 29227247, 2017). "Another finding showed that a dysfunctional or reduction in SOD1 expression favored the pathogenesis of H5N1 influenza virus and amyotrophic lateral sclerosis." (PMID 28512644, 2017).
amyotrophic lateral sclerosis (continued). "Amyotrophic lateral sclerosis (ALS) is a neurodegenerative disease involving the formation of cytoplasmic aggregates by proteins including TDP-43 and SOD1, in affected cells in the central nervous system (CNS)." (PMID 28711596, 2017). "Insoluble aggregates can be formed as a result of covalent cross-links among peptide chains, as in the case of amyloid-β-peptide (Aβ) in Alzheimer disease (AD), α-synuclein in Parkinson disease (PD), huntingtin in Huntington disease (HD), and SOD1 in amyotrophic lateral sclerosis (ALS)." (PMID 26881020, 2016). "In another study, exogenous delivery of miR-124a by stereotactic injection of neuronal cell-derived EVs prevented pathological loss of GLT1 protein, an important glutamate transporter, selectively lost in amyotrophic lateral sclerosis, in SOD1 G93A mice the experimental model of ALS." (PMID 27199663, 2016). "Autophagy clears aggregates, and factors involved in the process were analyzed in multiple areas of the CNS from human control subjects (n = 10) and amyotrophic lateral sclerosis (ALS) patients (n = 18) with or without SOD1 mutations." (PMID 26810478, 2016). "Impairments in mitochondria, oxidative regulation, and calcium homeostasis have been well documented in numerous Amyotrophic Lateral Sclerosis (ALS) experimental models, especially in the superoxide dismutase 1 glycine 93 to alanine (SOD1 G93A) transgenic mouse." (PMID 26190973, 2015). "Cu, Zn-Superoxide dismutase (SOD1) aggregation is a common hallmark of Amyotrophic Lateral Sclerosis (ALS) and the molecular mechanisms behind their formation are not completely understood." (PMID 25928076, 2015). "In an animal model of amyotrophic lateral sclerosis (ALS), mutant human superoxide dismutase 1 (hSOD1) transgenic mice, BV acupuncture inhibited microglia activation and phospho-p38 MAPK expression in the CNS, resulting in improvement of motor activity." (PMID 26131770, 2015). "In mice with a mutant form of superoxide dismutase 1 (SOD1), which develop a disease resembling amyotrophic lateral sclerosis (ALS), DMPO imaging was also successful in detecting free radicals." (PMID 25525560, 2014). "Regardless of its effect, it is still not clear whether spinal motoneurons are hyperexcitable in mutant superoxide dismutase 1 (mSOD1) mice, a standard model of amyotrophic lateral sclerosis (ALS)." (PMID 25313866, 2014). "Although the loss of motoneurons is an undisputed feature of amyotrophic lateral sclerosis (ALS) in man and in its animal models (SOD1 mutant mice), how the disease affects the size and excitability of motoneurons prior to their degeneration is not well understood." (PMID 25107988, 2014). "Postmortem of spinal cords presenting amyotrophic lateral sclerosis (ALS) and the erythrocytes of familial amyotrophic lateral sclerosis (FALS) with stable forms of mutant SOD-1 proteins show that Trx genes and protein expression are upregulated." (PMID 24723994, 2014). "Most ALS cases are sporadic amyotrophic lateral sclerosis(SALS) with only 5–10% genetically linked familial amyotrophic lateral sclerosis (FALS); 20% of FALS cases show missense mutations in the Cu/Zn superoxide dismutase (SOD1) gene." (PMID 24550780, 2014). "Because mitochondria have been implicated in the pathogenesis of amyotrophic lateral sclerosis (ALS), but the disease mechanisms are uncertain, we evaluated mitochondrial Dnmt3a and 5mC levels in human superoxide dismutase-1 (SOD1) transgenic mouse models of ALS." (PMID 24399935, 2013). "Similarly, theblockage of GAPDH synthesis was found for the first time to reduce the degreeof aggregation of mutant superoxide dismutase 1 (G93A) in a model ofamyotrophic lateral sclerosis (ALS)." (PMID 23819039, 2013).